CCR2 (C-C motif chemokine receptor 2)
Diseases named in the same sentence as CCR2 in open-access papers (continued):
Sharing a sentence is not in itself a finding about the gene and the disease.
arteriosclerosis (2 papers, 2003 to 2022). A vascular disorder characterized by thickening and hardening of the walls of the arteries. "Emerging evidence for the role of CCR-2 and CCR-5 receptors in human inflammatory diseases, arteriosclerosis and NASH has led to growing interest in developing CCR-2 and CCR-5 selective antagonists." (PMID 36694893, 2022). "The chemokine receptor CCR2, together with CCR5, plays an important role in the recruitment of monocytes/macrophages and T cells in various inflammatory diseases, infection and arteriosclerosis." (PMID 12644822, 2003).
atrial fibrillation (2 papers, 2024). A disorder characterized by an electrocardiographic finding of a supraventricular arrhythmia characterized by the replacement of consistent P waves by rapid oscillations or fibrillatory waves that vary in size, shape and timing and are accompanied by an irregular ventricular response. "In the case of atrial fibrillation (AFib), the most common type of arrythmia, the recruitment of a population of CCR2+ macrophages is a defining feature of this disorder." (PMID 38927523, 2024). "OPN-producing CCR2+ macrophages seem also to be involved in atrial fibrillation." (PMID 39595580, 2024). "In a mouse model of atrial fibrillation (the HOMER mouse), scRNASeq revealed the expansion of SPP1+CCR2+ monocyte-derived macrophages as a crucial event in rhythm abnormalities." (PMID 39595580, 2024).
benign breast tumors (2 papers, 2018 to 2022). "This demonstrates possible chance of using CCL2 and CCR2 in differentiation between benign breast tumor and healthy women." (PMID 30151375, 2018). "We also noticed statistical differences between the concentrations of CCL2 and CCR2 in patients with benign breast tumors and healthy controls (p<0.05)." (PMID 30151375, 2018). "Additionally, CCL2 and CCR2 levels may be useful in differentiation between benign breast tumor and healthy women." (PMID 30151375, 2018). "However, the concentration of CCR2 in stages II, III, and IV of BC was significantly lower when compared to the patients with benign breast tumors." (PMID 30151375, 2018).
bladder infection (2 papers, 2014 to 2018). "MCP-1/CCR2 axis induction within sacral DRGs has implications for bacterial pain phenotypes and clinical responses to bladder infection." (PMID 29739958, 2018). "CCL2/CCR2 interactions at the level of the urothelium and suburothelial nerve plexus in the urinary bladder are likely to contribute to bladder dysfunction and increased somatic sensitivity following CYP-induced cystitis." (PMID 24738044, 2014).
bone marrow fibrosis (2 papers, 2021 to 2022). "We then asked whether FCM detection of CCR2+ cells could be used as a diagnostic tool to track the progression of bone marrow fibrosis in MPNs." (PMID 36072806, 2022). "We found that the percentage of CCR2+ cells significantly increased with the grading of bone marrow fibrosis (r = 0.656, P< 0.0001, Spearman correlation)." (PMID 36072806, 2022). "Interestingly, overtPMF significantly overexpress CCR2 as compared to prePMF, suggesting that CCR2 expression on CD34+ circulating cells can be envisioned as a marker of bone marrow fibrosis (irrespective of rs1024611 SNP)." (PMID 34067466, 2021).
brain inflammation (2 papers, 2013 to 2021). "Thus, despite benefiting fungal clearance, the CCR2 axis contributed to severe CM symptoms and mortality that correlate with pathological evidence of brain inflammation." (PMID 34311579, 2021).
candidiasis (2 papers, 2025). Infection with the organism Candida. "Although trained immunity during invasive candidiasis is typically mediated by CCR2-monocytes and macrophages 5,6, our findings indicate that protection in the oral mucosa occurs independently of these cells." (PMID 40791350, 2025).
Chlamydia infection (2 papers, 2016 to 2025). "Conversely, our findings reveal that CCR2 deficiency leads to excessive Th2-type immune responses, characterized by increased production of IL-4 and IL-5, which compromise the host’s ability to effectively combat intracellular Chlamydia infections." (PMID 39903705, 2025). "An excessive Th2-type response can impair host resistance to intracellular Chlamydia infection, prompting us to examine IL-4, a key driver of Th2 differentiation, and evaluate its role in ccr2-/- mice." (PMID 39903705, 2025). "While CCR2, CCR5, CXCR6 and CD11c were preferentially expressed in a mouse model of Chlamydia infection, only CCR5 and CD11c were clearly expressed by effector T cells during bacterial vaginosis in women." (PMID 27272720, 2016). "The absence of CCR2 exacerbates C. muridarum infection in the respiratory tract by impairing the differentiation of CD4+ T cells into Th1 cells and reducing IFN-γ secretion, thereby weakening the immune response to Chlamydia infection." (PMID 39903705, 2025).
choroidal neovascularization (2 papers, 2011 to 2012). An eye disorder described by the growth of new blood vessels that originate from the choroid through a break in the Bruch membrane into the sub–retinal pigment epithelium (sub-RPE) or subretinal space. "Moreover, studies in experimental laser-induced choroidal neovascularization (CNV) have shown that ablation of either Ccl2 or the receptor Ccr2 inhibits the infiltration of monocytes/microglia and reduces lesion size following CNV." (PMID 22992301, 2012).
chronic prostatitis (2 papers, 2025). An infectious or non-infectious chronic inflammatory process that affects the prostate gland. "We conducted an allograft experiment to test, specifically, whether circulating CCR2+ cells mediate the fibrotic response to prostate inflammation." (PMID 39748675, 2025). "Because the roles of the CCL2/CCR2 axis in spinal macrophage recruitment have been elucidated, we focus on the roles of CXCL10 in neuroinflammation and pain in chronic prostatitis." (PMID 39718951, 2025).
clear-cell renal cell carcinoma (2 papers, 2016). "In this study, we aim to determine the prognostic value of CCL2 expression as well as its receptor C-C motif receptor type 2 (CCR2) in patients with non-metastatic clear cell renal cell carcinoma (ccRCC) after surgery." (PMID 27409666, 2016). "High expression of MCP-1 and CCR2 were significantly associated with shortened survival time and increased risk of recurrence in patients carrying non-metastatic clear-cell renal cell carcinoma and CCL2/CCR2 signature had a negative effect on overall survival and recurrence-free survival." (PMID 27788494, 2016).
colon adenoma (2 papers, 2021 to 2024). An adenoma that arises from the colon. "In contrast, CCR2 and CXCR5 were significantly downregulated during the colonic adenoma stage, with CCR2 (Log2FC = −1.02 ± 0.79) and CXCR5 (Log2FC = −1.42 ± 0.57)." (PMID 39409185, 2024). "The increasing abundance of CCR2-independent TRMs was observed in conjunction with colon adenoma progression due to CSF-1 depending on self-renewal." (PMID 33919979, 2021). "The kclTAMs came with more than 90%, while CCR2-independent TRMs accounted for less than 20% in the early stage of colon adenoma." (PMID 33919979, 2021).
cutaneous leishmaniasis (2 papers, 2023 to 2024). Leishmaniasis affecting the skin. "This is in contrast to its cognate receptor CCR2, which plays a crucial role in the protection against cutaneous leishmaniasis." (PMID 36675185, 2023). "During cutaneous leishmaniasis (CL), intermediate monocyte are reported to be a source of inflammatory cytokines IL-1β and TNF, and they express CCR2 attracting them to sites of inflammatory pathology." (PMID 38669292, 2024).
cystic fibrosis (2 papers, 2024). Autosomal recessive disorder caused by pathogenic variants in the CFTR gene (cystic fibrosis transmembrane conductance regulator), which encodes a chloride and bicarbonate channel expressed in epithelial cells, and follow the diagnosis criteria. "Similarly, in the lung affected by cystic fibrosis, CCR2+ monocytes/macrophages contribute to heightened levels of TGF-β in tissues and an increase in collagen production." (PMID 38977751, 2024).
cytomegalovirus infection (2 papers, 2014 to 2025). A herpesvirus infection caused by Cytomegalovirus. "Our findings emphasize the unique contributions of the coordinate activation of Cdc42 and Rac1, especially in CXCR2 and CCR2-mediated activation after HCMV infection." (PMID 40353220, 2025). "Thus, CXCR2 and CCR2 play different roles in the activation of Rho GTPases after HCMV infection." (PMID 40353220, 2025). "CCR2 and its ligand CCL2 are required for the mobilization of monocytes from the bone marrow and recruitment to the skin during murine cytomegalovirus infection and after exposure to ultraviolet light or chemical irritants." (PMID 25474197, 2014). "HCMV infection also induced cell contraction that was dependent on CXCR2, but not on CCR2, and it involved the activation of Rac1/Cdc42." (PMID 40353220, 2025).
dementia (2 papers, 2021 to 2025). Loss of intellectual abilities interfering with an individual's social and occupational functions. "Taken together, our results highlight a general mechanism that is needed to combat dementia, in which the CCR2/CCL2 axis, together with additional chemokines, such as Cxcl12, regulate the communication pathway between the brain and the immune system." (PMID 34172073, 2021). "This study describes the role of the CCR2/CCL2-axis in the communication between the brain and the immune system to combat dementia." (PMID 34172073, 2021).
diabetic retinopathy (2 papers, 2023). "CCR2+ inflammatory monocytes contribute to the pathogenesis of early lesions of diabetic retinopathy." (PMID 36698021, 2023). "Since nonclassical monocytes are not significantly affected by Ccr2 deletion, we suggest that CCR2+ monocytes play an important role in retinal leucostasis and leucocyte-mediated endothelial cell cytotoxicity in diabetic retinopathy." (PMID 36698021, 2023). "In this study, we focused on the effect of CCR2+ monocytes on molecular changes that are characteristic of early stages of diabetic retinopathy (such as oxidative stress and inflammation) and retinal capillary degeneration." (PMID 36698021, 2023).
dystrophinopathy (2 papers, 2021 to 2023). "Although Ly6chi monocytes were reduced out to 6 months of age in CCR2-deficient dystrophic mice, myonecrosis and fibrosis returned to control levels by this point, suggesting that other monocyte or macrophage populations promote dystrophinopathy at later stages of disease." (PMID 37418531, 2023). "Additionally, some treatments target the CCL2–CCR2 axis to improve muscle pathology in dystrophinopathy by decreasing the accumulation of monocytes/macrocytes, which can potentially affect the homing of CCR2-ADSCs." (PMID 33413615, 2021).
endometrial cancer (2 papers, 2021 to 2023). Primary or metastatic malignant neoplasm involving the endometrium (mucous membrane that lines the endometrial cavity). "Genetic studies confirm the association of the single nucleotide polymorphisms (SNPs) −2518 G>A (rs1024611) of the CCL2 gene and 190 G>A (rs1799864) of the CCR2 gene with the occurrence of endometrial cancer." (PMID 38001676, 2023). "The aim of our study is to reveal the role of CCR2 plays in the prognosis of patients with endometrial cancer and tumor microenvironment remodeling." (PMID 34251980, 2021). "Considering endometrial cancer, a significant relationship was noted between its incidence and pathogenesis on the one hand and CCL2, CCL5, and CXCL8 chemokines, and their selected receptors, including CCR2 (the receptor for CCL2) and CXCR2 (the receptor for CXCL8) on the other." (PMID 38001676, 2023).
endothelial dysfunction (2 papers, 2022 to 2025). In vascular diseases, endothelial dysfunction is a systemic pathological state of the endothelium (the inner lining of blood vessels) and can be broadly defined as an imbalance between vasodilating and vasoconstricting substances produced by (or acting on) the endothelium. "The critical roles of CCR2 and CXCR2 in further disruptions, such as endothelial dysfunction, smooth muscle cell proliferation, angiogenesis, and WBC infiltration/activation/adhesion highlight the importance of these receptors in vascular atherosclerosis." (PMID 40495291, 2025).
gastric tumor (2 papers, 2021 to 2024). "Human breast, ovarian, and gastric tumor cells cultured in vitro secrete CCL2; the cognate MDSCs from these patients express CCR2; and the recruitment of MDSCs to the tumor site is mediated by CCL2-CCR2 signaling." (PMID 34527668, 2021).
Graves disease (2 papers, 2023 to 2024). Graves' disease is an autoimmune disorder that leads to overactivity of the thyroid gland (hyperthyroidism).It is caused by an abnormal immune system response that causes the thyroid gland to produce too much thyroid hormones. "Most notably, Actinobacteria (p) presented protective effects on Hashimoto’s thyroiditis via CCR2 on myeloid Dendritic Cell (5.0%), and Bifidobacterium (g) showed facilitating effects on Graves’ disease through CD39+ CD4+ T cell %CD4+ T cell (5.0%) and CD14 on CD33+ HLA DR+ CD14dim (12.2%)." (PMID 39351300, 2024). "In comparison between Graves' disease (GD) patients and controls, genotype frequency of CCL17(rs223828)CC(OR = 0.4) was lower in the GD group, whereas those of CCR2(rs1799864)AA(OR = 4.8) were higher in the GD group." (PMID 37730733, 2023).
head and neck squamous cell carcinoma (2 papers, 2021). A squamous cell carcinoma that arises from any of the following anatomic sites: lip and oral cavity, nasal cavity, paranasal sinuses, pharynx, larynx, and salivary glands. "RT can also upregulated CCL2 chemokine in tumor cells, leading to a CCR2-dependent accumulation of tumor necrosis factor alpha (TNFα)-producing monocytes and CCR2+ regulatory T cells (Treg) in a murine model of head and neck squamous cell carcinoma." (PMID 34094967, 2021). "In a head and neck squamous cell carcinoma (HNSCC) murine model, researchers found that RT could upregulate CCL2 production and induce the CCR2-dependent accumulation of Tregs and TNF α-producing monocytes and macrophages, thereby playing an immunosuppressive role." (PMID 33789758, 2021).
Headache (2 papers, 2013 to 2024). Cephalgia, or pain sensed in various parts of the head, not confined to the area of distribution of any nerve. "In this study, we asked whether repeated sumatriptan administration in mice alters the level of CCL2 and CCR2 mRNA expression in dura and trigeminal ganglion (TG), tissues that are strongly implicated in headache generation." (PMID 39528947, 2024).
helminth infection (2 papers, 2018 to 2025). "In helminth infections, this axis is crucial for Th2 responses, as was demonstrated in Schistosoma mansoni-infected Ccr2-deficient mice, which exhibited defective monocytes and macrophages, and reduced IL-4 production." (PMID 40872306, 2025).
hemorrhage (2 papers, 2022 to 2024). Loss of blood from the vascular compartment to the exterior or into nonvascular body space as a result of rupture or severance of the blood vessels. "A small number of T. gondii was observed in the placenta because of infection in the WT samples, whereas a large number of T. gondii was observed in the CCR2-deficient samples, especially around the hemorrhage area." (PMID 39051675, 2024).
Ileitis (2 papers, 2012 to 2020). "Superimposition of genetic susceptibility and T. Gondii infection revealed greatest dysbiosis and bacterial invasion in the CD-susceptible genotype, NOD2−/−, and reduced dysbiosis in ileitis-resistant CCR2−/− mice." (PMID 22848538, 2012).
invasive breast carcinoma (2 papers, 2017 to 2021). A carcinoma that infiltrates the breast parenchyma. "Addressing these questions would provide an important justification to further develop the CCL2/CCR2 pathway as a predictive signature and in approaches to prevent invasive breast cancer." (PMID 33888841, 2021).
invasive breast ductal carcinomas (2 papers, 2019 to 2021). "Through analysis of patient derived breast tissues and mouse models of DCIS, we showed that expression of CCL2, CCR2, phospho-SMAD3 and phospho-p42/44MAPK proteins were associated with invasive breast ductal carcinomas." (PMID 33888841, 2021). "In previous studies, we had ablated CCR2 gene expression in DCIS.com cells by CRISPR (CCR2-KO), which inhibited formation of invasive ductal carcinomas." (PMID 31208996, 2019).
Japanese encephalitis (2 papers, 2017). A disease due to a virus transmitted by an arthropod). "This is in contrast to observations in a Japanese encephalitis model, in which CCR2−/− mice had reduced monocyte infiltration while CCL2−/− mice had a paradoxical increase in this population in the brain." (PMID 29202854, 2017).
joint disease (2 papers, 2011 to 2024). "With the emergence of targeted therapies for various chronic inflammatory diseases, such as RA and OA, focusing on the CCL2/CCR2 axis and its clinical implications can offer new perspectives on how to manage these common and debilitating joint diseases." (PMID 39076996, 2024). "However, such significant elevation of sera cytokines in CCR2−/− mice became less obvious when robust joint disease developed." (PMID 21991368, 2011).
keloid (2 papers, 2023 to 2025). An irregularly shaped, elevated mark on the skin caused by deposits of excessive amounts of collagen during wound healing. "CCL2 and CCR2 expression is reportedly enhanced in keloid tissue, increasing fibroblast proliferation." (PMID 37524866, 2023).
keratoconus (2 papers, 2023 to 2024). A degenerative, structural disorder of the eye, characterized by a cone-shaped protrusion of the cornea. "However, it was observed that the expression of CCR2 was significantly reduced in individuals with keratoconus in the external validation cohort, while it was significantly increased in the test cohort." (PMID 38830963, 2024). "The expression of CCR2, CDKN1A, HSPA5, MAPK8IP1, PPP1R15A, and VEGFA in individuals with keratoconus was significantly different from that in control subjects." (PMID 38830963, 2024). "Ultimately, it was found that the chemokine receptors CCR2 and CCR5, as well as F2RL1 and CXCL5, may be involved in the immune regulation process of keratoconus." (PMID 37965330, 2023).
left ventricular hypertrophy (2 papers, 2014 to 2025). Enlargement of the LEFT VENTRICLE of the heart. "Here, we analyzed the role of CCR2 in the development of left ventricular hypertrophy using Ccr2-/- mice." (PMID 40257974, 2025). "In summary, our findings demonstrate that CCR2-dependent recruited macrophages play a role in the development of left ventricular hypertrophy (LVH)." (PMID 40257974, 2025). "In this study, we examined the role of CCR2 in the development of left ventricular hypertrophy using Ccr2-/- mice." (PMID 40257974, 2025).
leishmaniasis (2 papers, 2014 to 2024). Infectious disease that is transmitted through the bite of hematophagous female phlebotomine sand flies. "The association between CCR2 and T cells in the context of Leishmaniasis has not been extensively studied compared to other chemokine receptors such as CCR1, CCR3, and CXCR3." (PMID 39587036, 2024).
leukocytosis (2 papers, 2018 to 2022). "The increased blood concentrations of leukocytes (which did not, however, exceed the leukocytosis level) in patients treated with Ca-antagonists seem to be a compensatory reaction against the increased number of leukocytes with the invalid MCP-1/CCR2 pathway." (PMID 30208601, 2018).